PTGES (prostaglandin E synthase)
Description:
Terminal enzyme of the cyclooxygenase (COX)-2-mediated prostaglandin E2 (PGE2) biosynthetic pathway. Catalyzes the glutathione-dependent oxidoreduction of prostaglandin endoperoxide H2 (PGH2) to prostaglandin E2 (PGE2) in response to inflammatory stimuli. Plays a key role in inflammation response, fever and pain (By similarity). Also catalyzes the oxidoreduction of endocannabinoids into prostaglandin glycerol esters and PGG2 into 15-hydroperoxy-PGE2. In addition, displays low glutathione transferase and glutathione-dependent peroxidase activities, toward 1-chloro-2,4-dinitrobenzene and 5-hydroperoxyicosatetraenoic acid (5-HPETE), respectively.
Synonyms: MGST1-L1; MPGES-1; MGST1L1; PGES; PIG12; MGST-IV; TP53I12; MPGES; PP102; PP1294
Tractability: Small molecule: a structure with a bound ligand is known; a high-quality ligand is known; it has a high-quality binding pocket; it belongs to a druggable protein family. Antibody: UniProt predicts a signal peptide or a membrane-spanning region. PROTAC: a small molecule that binds it is known.
Target class: Isomerase; Enzyme
Chemical probes: GRC-27864, PD085364, mPGES1-IN-3 (high quality)
Safety:
Unwanted effects reported when the protein is acted on. In parentheses: how it was acted on, where the effect was seen, and who reports it.
cardiovascular toxicity (source: ClinPGx)
cardiovascular toxicity and symptoms (source: ClinPGx)
Gene: Protein-coding gene on chromosome 9 (129,738,331 to 129,753,042, reverse strand). Ensembl gene ENSG00000148344.
Subcellular location: Membrane; Cytoplasm, perinuclear region
Subcellular location (Human Protein Atlas): Endoplasmic reticulum
Pathways (Reactome):
Metabolism: Synthesis of Prostaglandins (PG) and Thromboxanes (TX)
Gene Ontology:
Molecular function: glutathione binding; glutathione peroxidase activity; glutathione transferase activity; prostaglandin-E synthase activity; protein binding; phospholipid-hydroperoxide glutathione peroxidase activity; prostaglandin-D synthase activity
Biological process: prostaglandin biosynthetic process; prostaglandin metabolic process; regulation of fever generation; regulation of inflammatory response; sensory perception of pain; signal transduction; cellular oxidant detoxification; cyclooxygenase pathway
Cellular component: endoplasmic reticulum; membrane; endoplasmic reticulum membrane; cytoplasm; nuclear envelope lumen; perinuclear region of cytoplasm
Genetic constraint (gnomAD): Loss-of-function variants: 3 observed, 8.05 expected, observed/expected ratio (o/e) 0.37, 90% interval 0.17 to 0.96. That is too few expected variants to judge how well the gene tolerates losing a copy. Missense variants: 180 observed, 186.88 expected, observed/expected ratio (o/e) 0.96, 90% interval 0.85 to 1.09. Synonymous variants: 94 observed, 77.23 expected, observed/expected ratio (o/e) 1.22, 90% interval 1.03 to 1.45.
Homologues: Orthologues: chimpanzee PTGES (98% identical), macaque PTGES (98% identical), pig PTGES (87% identical), dog PTGES (84% identical), guinea pig PTGES (83% identical), rat Ptges (80% identical), mouse Ptges (80% identical), zebrafish ptges (60% identical), tropical clawed frog ptges (59% identical), Drosophila melanogaster CG33178 (34% identical), Drosophila melanogaster Mgstl (34% identical), Drosophila melanogaster CG33177 (31% identical). Paralogues in human: MGST1 (37% identical).
Diseases named in the same sentence as PTGES in open-access papers:
PTGES is named in the same sentence as 175 diseases in open-access papers, as found by Europe PMC text mining. Sharing a sentence is not in itself a finding about the gene and the disease. The quoted sentences say what the papers report.
lung carcinoma (19 papers, 2017 to 2025). "Moreover, high‐expression PTGES was associated with poor overall survival in patients with lung cancer." (PMID 39417702, 2024). "Furthermore, PTGES was upregulated in lung tumours and was associated with poor overall survival in patients with lung cancer." (PMID 39417702, 2024). "As expected, PTGES was upregulated in lung cancer tumours and IPF‐affected lungs compared with healthy tissues." (PMID 39417702, 2024). "MDSC number is revealed to abnormally increase in lung cancer in a Gprc5a-knockout mouse model, which promotes lung cancer metastasis regulated by enhanced prostaglandin E synthase (PTGES)/PGE2 signaling." (PMID 34689842, 2021). "The dysregulated PTGES promoted tumor migration and metastasis of lung cancer cells and played an important role in lung cancer progression." (PMID 33344071, 2020). "In GPRC5A-knock out mice, prostaglandin E2 synthase (PTGES)/prostaglandin E2 (PGE2) signaling is highly associated with tumorigenesis and metastasis and is related to immune suppression in lung cancer." (PMID 32325999, 2020). "Our recent study demonstrated that Dioscorea japonica extract suppressed the expression of cyclooxygenase-2 and microsomal prostaglandin E synthase-1 and induced apoptosis in lung carcinoma A549 cells." (PMID 29610553, 2018). "In silico and qRT-PCR analysis clearly supported the notion that, NRF2 directly binds to the ARE sequences located in the promoter regions of ALDH3B1, NAMPT, and PTGES genes and induces their expression in lung cancer." (PMID 29050246, 2017). "Moreover, lung cancer patients with either low GPRC5A or high PTGES expression exhibited poor overall survival." (PMID 32060421, 2020). "It was also reported that the aberrant expression in the NSCLC cell lines and PTGES knockdown could significantly suppress the migration of lung cancer cell." (PMID 32684932, 2020). "Here, we speculate that NRF2 induces stemness in lung cancer cells via the transactivation of PTGES gene expression." (PMID 29050246, 2017). "Therefore, ROB targeting PTGES may be meaningful targets for the treatment of lung cancer." (PMID 39450260, 2024). "Next, PTGES, ST8SIA1 and PTGS2 expression levels were evaluated in patients with lung cancer (GSE31210) and IPF using microarray datasets." (PMID 39417702, 2024). "PTGES, the key enzyme for the synthesis of PGE2 in the AA pathway, was demonstrated to be essential for the tumorigenicity, migration, and metastasis of non‐small cell lung cancer (NSCLC) cells." (PMID 37180822, 2023). "Taken together, these results suggest that the PTGES/PGE2 pathway is essential for the enhanced stemness and pro-metastatic features in human NSCLC and mouse lung cancer cells." (PMID 32060421, 2020). "Researchers have identified multiple signaling pathways involved in lung cancer chemoresistance, including cyclooxygenase-2 (COX-2)/microsomal prostaglandin E synthase-1 (mPGES-1) derived prostaglandin E2 (PGE2)." (PMID 33473256, 2020). "A total of 83 potential targets of ROB in lung cancer were collected and further screened by using Cytoscape software, and 7 targets of PTGS2, CYP19A1, PTGS1, AR, CYP17A1, PTGES and SRD5A1 were obtained as hub genes and 7 hub targets had good binding energy with ROB." (PMID 39450260, 2024). "Of those identified target genes, we selected HSPA6, histidine‐rich glycoprotein (HRG), ubiquitin D, prostaglandin E synthase (PTGES), tyrosine kinase (TXK), and MMP2 and measured those gene expressions in eight lung cancer cells 48 h after treatment with acRoots at 10 mg/mL." (PMID 32508044, 2020). "We speculated that PTGES expression was upregulated in patients with IPF and lung cancer." (PMID 39417702, 2024). "The hub targets of ROB action in lung cancer were further analyzed by combining 14 targets from Degree≥6, 10 targets each from MCC and MNC algorithms, and finally 7 common targets such as PTGS2, CYP19A1, PTGS1, AR, CYP17A1, PTGES and SRD5A1 were obtained from the final screening." (PMID 39450260, 2024).
lung carcinoma (continued). "However, miR-574-5p has recently been shown to positively regulate the expression of microsomal prostaglandin E-synthase-1 (mPGES-1), a key enzyme in the prostaglandin E2 (PGE2) biosynthesis, by acting as decoy to the RNA-binding protein CUG-RNA binding protein 1 (CUGBP1) in human lung cancer." (PMID 32231562, 2020).
breast cancer (14 papers, 2015 to 2022). A primary or metastatic malignant neoplasm involving the breast. "Recent studies have implicated the role of microsomal prostaglandin E synthase-1 (mPGES-1) in several solid tumours, such as breast cancer, prostate cancer and colon cancer." (PMID 32251289, 2020). "PTGIS, PTGES, and PTGER4 up-regulation in the group of responders with HER2-positive breast cancer, known by its aggressive behavior, is associated with complete tumor response to treatment with fluorouracil, epirubicin, and cyclophosphamide (FEC)." (PMID 35453789, 2022). "They found that breast cancer cells elicit induction of the COX-2/microsomal prostaglandin-E synthase-1 axis in MSCs recruited into the pre-metastatic niche by releasing IL-1 which elicits a mesenchymal/stem cell-like phenotype in the breast cancer cells." (PMID 30847298, 2019). "Considering that E2 and G-1 trigger the expression of IL1β in CAFs and IL1R1 in breast cancer cells, we then assessed that conditioned medium from CAFs exposed to E2 and G-1 does induce PTGES protein expression in SkBr3 and MCF-7 cells exposed to E2 or G-1." (PMID 27072893, 2016). "Some other transcriptionally regulated targets of E2 that induce breast cancer cell proliferation are hes family bHLH transcription factor 6 (Hes-6), prostaglandin E synthase (PTGES), alkaline phosphatases (ALP) and the LRP16 gene, just to mention a few." (PMID 27160081, 2016). "Other treatment targets, such as specific PGE2 receptor antagonists or synthesis inhibitors (for example, against PTGES), may be valuable in the prevention of tumor proliferation, invasion, and metastasis of breast cancer." (PMID 35127497, 2021). "Western blot analysis showed that compared to control HMEC cells, expression of the G-protein coupled EP receptors, EP1-4, COX-2 and microsomal prostaglandin E synthase-1 (mPGES-1) were significantly upregulated in the breast cancer cells SUM149PT and SUM1315MO2." (PMID 27270654, 2016). "For instance, IL1β/IL1R1 system has been shown to up-regulate PTGES, which is a key enzyme involved in the production of COX2 and prostaglandin E2 that promote the motility of breast cancer cells." (PMID 27072893, 2016).
colon carcinoma (14 papers, 2011 to 2024). "This signaling provides a molecular explanation to PTGS2 and PTGES association and contribute to colon cancer advance, pointing out novel potential therapeutic targets in this oncological context." (PMID 26498686, 2015). "Gene expression of GABRB3, GABRG2, and GAD1 positively correlated with genes involved in the synthesis of PGE2 (PTGS2 and PTGES) as well as IL‐6 in human colon cancer." (PMID 38886975, 2024). "Our results describe for the first time the molecular pathway correlating PTGS2 and PTGES in colon cancer progression." (PMID 26498686, 2015).
melanoma (11 papers, 2015 to 2025). A malignant, usually aggressive tumor composed of atypical, neoplastic melanocytes. "Amplification or overexpression of PTGES/PTGES2 in melanoma samples was associated with a significantly lower patient survival, emphasising the significance of our findings." (PMID 31819183, 2020). "To evaluate the specific contribution of PGE2, we generated BrafV600E melanoma cells genetically deficient in microsomal prostaglandin E synthase (mPGES)-1 and -2 (referred to as Pges−/− cells), two of the enzymes specifically required for the synthesis of PGE2, but not other prostanoids." (PMID 26343581, 2015). "In another study, PTGES inhibitor Cay10526 was shown to inhibit subcutaneous melanoma tumor growth in nude mice at high doses (50 mg/kg)." (PMID 32060421, 2020). "We showed that COX2 and PTGES are both overexpressed in several BRAF/MEKi-resistant melanoma cells and tumor tissues, and that COX2 knockdown significantly enhanced drug effects in melanoma cell." (PMID 32967672, 2020). "Prostaglandin synthase (PTGES) expression was inversely correlated with melanoma patient survival." (PMID 31819183, 2020).
glioma (10 papers, 2016 to 2025). A benign or malignant brain and spinal cord tumor that arises from glial cells (astrocytes, oligodendrocytes, ependymal cells). "The IGLoS signature consists of six immune infiltration‐related genes associated with the survival of diffuse patients with glioma, which are CCL19, ICOSLG, IL11, PTGES, TNFAIP3, and TRAF3IP3." (PMID 40714831, 2025). "Prostaglandin E2 (PGE2) is another unsaturated fatty acid and known as an inducer of inflammation and pain, which was catalyzed from AA by cyclooxygenase (COX)-2 and prostaglandin E synthase (PGES) overexpressed in glioma cells, especially mesenchymal cells." (PMID 34211978, 2021). "In the Gusu in‐house dataset consisting of 24 patients with glioma, TRAF3IP3, TNFAIP3, ICOSLG, IL11, and PTGES, showed a trend of increasing expression with increasing tumor grade, whereas CCL19 was not." (PMID 40714831, 2025). "Next, we used the LASSO regression to further select six key regulators consisting of CCL19, ICOSLG, IL11, PTGES, TNFAIP3, and TRAF3IP3, and they were named the Immune Glioma Survival Signature (IGLoS signature)." (PMID 40714831, 2025). "Arachidonic acid (AA) metabolic enzymes including cyclooxygenase-2 (COX-2), microsomal prostaglandin E synthase-1 (mPGES-1) and cytochrome P450 (CYP) 4A11 play important roles in glioma angiogenesis." (PMID 31438982, 2019). "In addition, Arachidonic acid (AA) metabolic enzymes, including microsomal prostaglandin E synthase-1 (mPGES-1), cyclooxygenase-2 (COX-2) and CYP4A11, are vital to glioma angiogenesis." (PMID 34368156, 2021).
colitis (8 papers, 2018 to 2025). Inflammation of the colon. "In a DSS-induced colitis model, pomegranate extract was demonstrated to lessen the severity of colitis by modulating the gut microbiota and down-regulating COX-2, PTGES, iNOS, and PGE2 expression." (PMID 35405802, 2022).
neuroblastoma (8 papers, 2010 to 2024). Neuroblastoma (NB) is the most common solid, extracranial childhood tumor. "In neuroblastoma (NB), an endocrine tumor of early childhood, we found that CAFs are the major source of microsomal prostaglandin E synthase‐1 (mPGES‐1), the key enzyme responsible for PGE2 production in tumors downstream of cyclooxygenase (COX)‐1/2." (PMID 37519014, 2024). "Medulloblastoma, PNET and neuroblastoma primary tumours express high levels of COX-2 and microsomal prostaglandin E synthase-1 (mPGES-1), the two enzymes responsible for converting arachidonic acid, a dietary fatty acid and precursor to eicosanoid synthesis, to prostaglandin E2." (PMID 22276025, 2010). "However, in a preclinical study, specific pharmacological inhibition of microsomal prostaglandin E synthase-1 (mPGES-1) by non-toxic single drug CIII effectively blocked CAF-derived PGE2 production and modulated the neuroblastoma microenvironment towards being less tumor-promoting." (PMID 32422889, 2020).
prostate carcinoma (8 papers, 2016 to 2025). A carcinoma that arises from epithelial cells of the prostate gland. "Aggressiveness of cancers, like prostate cancer, has been found to be associated with elevated expression of the microsomal prostaglandin E synthase-1 (mPGES-1)." (PMID 34242345, 2021). "The robust tumorigenic drive of DU145 prostate cancer cells has been associated with constitutive over-expression of microsomal prostaglandin E synthase-1 (mPGES-1) and higher output of PGE-2, which, in turn, impinges on several pro-tumorigenic pathways such as EGFR and Wnt." (PMID 27322147, 2016). "A study on microsomal prostaglandin E synthase-1 (mPGES-1) discovered that host stromal mPGES-1-induced PGE2 upregulates SDF-1 in a murine model of lung metastasis from prostate cancer." (PMID 34689842, 2021). "A recent interesting study on prostate cancer cells has shown that PTGES amplifies epidermal growth factor receptor-driven tumor progression and induces stemness and invasiveness." (PMID 29050246, 2017).
rheumatoid arthritis (8 papers, 2011 to 2024). A chronic, systemic autoimmune disorder characterized by inflammation in the synovial membranes and articular surfaces. "PGE-2 production is mediated by the cyclooxygenase (COX-1/2) and microsomal prostaglandin E synthase-1 (mPGES-1) enzymes, and it serves as a pro-inflammatory mediator involved in cardiovascular disease, rheumatoid arthritis, and various cancers." (PMID 39267848, 2024). "Also, PTGES has also been reported to play a vital role in other autoimmune diseases, including ulcerative colitis and rheumatoid arthritis." (PMID 37867507, 2023).
colorectal cancer (7 papers, 2015 to 2025). A primary or metastatic malignant neoplasm that affects the colon or rectum. "PTGES on the other hand, which encodes mPGES1, was found significantly increased in 3 analyses of colorectal cancer vs. normal tissue, as well as in 8 other cancer type datasets." (PMID 26498686, 2015). "In colorectal cancer, garcinol was noticed to target prostaglandin E synthase (PTGES) and thus decrease PGE2 productions." (PMID 34575983, 2021). "In colorectal cancer, garcinol has been reported to act through microsomal prostaglandin E synthase-1 (mPGES-1)/prostaglandin E synthase 2 (PGE2)/hypoxia inducible factor-1 alpha (HIF-1α) axis in HT-29 cells." (PMID 32365899, 2020).
osteoarthritis (7 papers, 2006 to 2023). A noninflammatory degenerative joint disease occurring chiefly in older persons, characterized by degeneration of the articular cartilage, hypertrophy of bone at the margins and changes in the synovial membrane. "Moreover, we explored the interlink or sub-cellular localization of pleckstrin with microsomal prostaglandin E synthase-1 (mPGES-1), an important key enzyme of inflammation processes involved in numerous chronic inflammatory diseases including RA, osteoarthritis, and periodontitis." (PMID 35087525, 2021). "Microsomal prostaglandin E synthase 1 (mPGES-1) catalyzes the terminal step in the biosynthesis of PGE2, a critical mediator in the pathophysiology of osteoarthritis (OA)." (PMID 24886859, 2014).
glioblastoma (5 papers, 2011 to 2025). The most malignant astrocytic tumor (WHO grade IV). "Also, the PTGES gene, encoding prostaglandin E synthase (which plays a key role in inflammation and immune response) was shown to be dysregulated in a comparison between glioblastoma and lung adenocarcinoma." (PMID 38612755, 2024). "The expression of PTGES varies among TCGA tumors and is related to the poor prognosis of glioblastoma multiforme, kidney renal clear cell carcinoma, liver hepatocellular carcinoma, rectal adenocarcinoma, and uveal melanoma." (PMID 35664305, 2022). "Comparison of PTGES expression between normal tissues and cancer patient tissues of multiple cancers revealed significantly higher expression (>3-fold change) of PTGES mRNA in cholangiocarcinoma, diffuse large B cell lymphoma, glioblastoma, pancreatic cancer, and thymoma." (PMID 37108468, 2023).
inflammatory bowel disease (5 papers, 2015 to 2025). A spectrum of small and large bowel inflammatory diseases of unknown etiology. "Other research has shown that exogenous nicotinamide adenine dinucleotide promotes the expression of PTGES and maintains the integrity of the mucus layer that modulates immune response appropriately and therefore participates in the pathological process of inflammatory bowel diseases." (PMID 37867507, 2023).